STAT3 (signal transducer and activator of transcription 3)
Diseases named in the same sentence as STAT3 in open-access papers (continued):
Sharing a sentence is not in itself a finding about the gene and the disease.
colon carcinoma (continued). "IL-11 stimulation-induced phosphorylation of STAT3 in AKTP tumor organoids and human colon cancer cell lines." (PMID 33863879, 2021). "Using in silico site-directed fragment-based drug design (FBDD), the small-molecule STAT3 inhibitor LY5, an analog of STA-21, was tested in colon cancer cells." (PMID 32872659, 2020). "Colivelin, an agonist of JAK2/STAT3 pathway, antagonized the tumour‐suppressive effect of OCA on colon cancer cells." (PMID 33164339, 2020). "Next to STAT3, NF-κB and downstream targets, such as SNAI1, cooperate with STAT3 in promoting the progression of colon cancer metastasis by conferring apoptosis resistance and epithelial plasticity." (PMID 32222879, 2020). "In the present study, the FXR agonist OCA inhibited colon cancer cell proliferation and invasion by repressing JAK2/STAT3 pathway via regulating SOCS3 transcription." (PMID 33164339, 2020). "Mechanistically, FAL1 interacts with STAT3 and triggers its phosphorylation to modulate the expression of Bcl-2, TGF-β1, p65, and PCNA in colon cancer cells." (PMID 33246471, 2020). "Metformin, in combination with 5-fluorouracil and oxaliplatin (FuOX), induced cell death in chemoresistant colon cancer cells by suppressing cancer stem cells (CSC) characteristics, STAT3, and NF-κB activation and suppressing STAT3 and NF-κB activation." (PMID 32754598, 2020). "In order to determine that JAK2/STAT3 signalling is indispensable for the tumour‐suppressive effect of FXR activation on colon cancer cells, colivelin and IL‐6, the agonists of JAK/STAT3 pathway, were adopted to treat FXR‐activated cells." (PMID 33164339, 2020). "It has been reported that IL-6 activates expansion of MDSCs via the JAK2/STAT3/NF-κB signaling pathway, resulting in AOM/DSS-induced colon tumor development in G protein subunit alpha i1 (GNAI1) and GNAI3 (GNAI1;3) double-knockout (DKO) mice." (PMID 33384962, 2020). "The expression of GP130, IL-11, IL-11 receptor α (IL-11Rα), IL-6, IL-6 receptor (IL-6R) and STAT3 activation were examined by western blot in DLD-1, HCT-15, and HCT-116 colon cancer cell lines." (PMID 30736824, 2019). "Recently, we found activated signal transducer and activator of transcription 3 (STAT3) is upregulated by interleukin (IL)-6 and blocking of the STAT3/CD133/survivin signaling pathway showed anticancer effect in colon cancer in vitro." (PMID 31393941, 2019). "Therefore, HNF3β probably regulates STAT3 signaling via the network including those and more other molecules, and inhibition of this inflammatory signaling pathway may be the mechanism through which HNF3β inhibits the malignant progression of colon cancer." (PMID 31696055, 2019). "Other study showed that napabucasin, which inhibits STAT3-driven gene transcription, blocks several key molecules in CSC-related signaling pathways, including c-Myc, Nanog and Sox2, in a colon cancer mouse model, thereby suppressing metastases." (PMID 31137841, 2019). "SB225002, an antagonist of CXCR2, reduced Tyr705 phosphorylation of STAT3 and IL‐8 protein expression in HCT116 colon cancer cells, which was also apparent in HCT116 sh‐ZNF143 cells." (PMID 30933430, 2019). "Colon tumor from LysM-tRXRα mice also showed a significant elevated level of TRAF6 expression, which positively correlated with STAT3 activation." (PMID 30931933, 2019). "IL-6-mediated activation of STAT3 in colon cancer cell lines was shown to occur in conjunction with the phosphorylation (inactivation) of RKIP, leading to poor prognosis of colon cancer stage II patients." (PMID 30149591, 2018). "In the present study, we validated that miR‐181b activated STAT3 in colon cancer cells, and furthermore PIAS3 mediated the effect of miR‐181b on STAT3 activation." (PMID 30054984, 2018). "STAT3, the main downstream target of JAK2, plays an essential role in proliferation and survival in colon cancer-initiating cells." (PMID 30564118, 2018).
colon carcinoma (continued). "On the basis of the evidence presented above, we propose that RAB3C overexpression in colon cancer cells induces IL-6 exocytosis, thereby triggering JAK2 activation and STAT3 phosphorylation and inducing cancer cell metastasis." (PMID 28784136, 2017). "One example is the role of S1P in the IL-6/STAT3 pathway (interleukin 6/signal transducer and activator of transcriptional factor STAT3), which is involved in IBD pathophysiology and colon cancer development." (PMID 28362332, 2017). "In this network diagram, many genes were closely related with colon cancer progression such as PTEN, STAT3, FOXO1, and SMAD4." (PMID 28938919, 2017). "STAT3, a member of the STAT family of transcription factors, is frequently activated in many types of cancers including liver and colon cancers." (PMID 26883202, 2016). "The IL-32θ-induced inhibition of STAT3 results in the downregulation of ZEB1, Bmi1 and also upregulation of E-cadherin signaling in colon cancer cells." (PMID 26824417, 2016). "Inhibition of persistent STAT3 phosphorylation by LY5 also inhibited colony formation, cell migration, and decreased the viability of liver cancer and colon cancer cells." (PMID 26883202, 2016). "The inhibitory effect on STAT3 phosphorylation, cell viability, migration and colony forming ability by LY5 were examined in human liver and colon cancer cells." (PMID 26883202, 2016). "We have shown that dual inhibition of STAT3 and MEK using the STAT3 inhibitor LY5 and MEK inhibitor Trametinib exerts significant anti-tumor cell efficacy in K-Ras mutant pancreatic and colon cancer cells in vitro." (PMID 25961376, 2015). "In this study, we identified the JAK2/STAT3 pathway as a key mediator of the resistance to MEK inhibition in K-Ras mutant pancreatic and colon cancer cells." (PMID 25961376, 2015). "Trametinib decreased ERK phosphorylation in K-Ras mutant colon cancer cells, while it also induced a strong expression of P-JAK2 and a moderate expression of P-JAK3, the upstream kinases that phosphorylate STAT3 (HCT116 cells as a representative)." (PMID 25961376, 2015). "The inhibitory effects of EVO on JAK2/STAT3 signaling and MMP3 expression were stronger than those of AG490, suggesting that EVO is a strong inhibitor of tumor cell migration in colon cancer." (PMID 26580615, 2015). "Here, we identified that Signal Transducer and Activator of Transcription 3 (STAT3) was significantly activated following the MEK inhibition using AZD6244, PD98059 and Trametinib in K-Ras mutant pancreatic and colon cancer cells." (PMID 25961376, 2015). "Knock down of STAT3 or p50 magnified the cell growth inhibitory effect of (E)-4-(3-(3,5-dimethoxyphenyl)allyl)-2-methoxyphenol in HCT116 and SW480 colon cancer cells." (PMID 26474284, 2015). "Using genetic, functional, and pharmacologic inhibition, we have demonstrated that dual inhibition of STAT3 and MEK signaling pathways significantly reduced viability of pancreatic and colon cancer cells." (PMID 25961376, 2015). "In the analysis of tumor samples from stage II colon cancer patients and the human colon carcinoma cell line HCT116, pRKIP and STAT3, 2 proteins potentially involved in the resistance to conventional treatments were detected." (PMID 24098947, 2013). "In colon cancer cells, CD44 translocates into nucleus and directly interacts with STAT3 in response to osteopontin." (PMID 23326564, 2013). "In colon cancer cells (HT-29), EGF-induced PI-3K/STAT3 signaling was suggested as an essential pathway regulating VEGF and leptin expression." (PMID 24202338, 2013). "We extended these observations and determined STAT3 and RKIP/ pRKIP in tumor microarrays (TMA) in stage II colon cancer patients." (PMID 24098947, 2013). "Our results indicated that curcumin inhibited STAT3 phosphorylation, cell viability, and tumoursphere formation in ALDH+/CD133+ colon cancer stem cells." (PMID 21694723, 2011).
colon carcinoma (continued). "Our results indicated that GO-Y030 significantly inhibited STAT3 phosphorylation (Y705) in DLD-1, HCT-116, and SW480 human colon cancer cell lines." (PMID 21694723, 2011). "To investigate the specific inhibition of GO-Y030, we detected the phosphorylation of STAT3, STAT1, or STAT6 induced by IL-6, IFN-γ, or IL-4 in HT29 colon cancer cell lines." (PMID 21694723, 2011). "Stattic and WP1066 were also found to inhibit STAT3 phosphorylation and induce apoptosis indicated by the cleaveage of capase-3 in HCT116 colon cancer cells and U266 multiple myeloma cells." (PMID 20712901, 2010). "Our results indicated that IRSp53 is a substantial aim in colon cancer remedy and secretome of hAMSCs suppresses IRSp53 expression as well as related molecules such as IRSp53, p-AKT (Ser 473), p-Stat3 (Tyr 705), and cyclin D1 in the HT-29 colon cancerous cell line." (PMID 41200137, 2025). "In colon cancer, TNF-α stimulates transcription factors like nuclear factor kappa-light-chain-enhancer of activated B cells (NF-κB) and signal transducer and activator of transcription 3 (STAT3), which promote angiogenesis, cell proliferation, survival, and immune evasion." (PMID 40558596, 2025). "Unfortunately, so far this is the only study that provides evidence for this correlation and there was no study found regarding the association of STAT3 and CCL3 in colon cancer." (PMID 41153795, 2025). "Gefitinib has been described able to decrease synthesis of matrix metalloproteinase of colon cancer cells, and more recently miRNA-124 showed to indirect inhibit MMP9 via the transcription factor Signal transducer and activator of transcription 3 (STAT3) modulation." (PMID 40573308, 2025). "Butyrate also inhibits STAT3 signaling, thus suppressing the expression of bcl-2, bcl-XL, c-myc, cyclin D1, and HIF-1, resulting in decreased cell proliferation and increased apoptosis in both hypoxia and in colon cancer." (PMID 40699627, 2025). "Blocking LIF in a mouse model of colon carcinoma prevented the initiation and progression of cancer cachexia (e.g., muscle wasting) via the Janus kinase 2–signal transducer and activator of transcription 3 (JAK2–STAT3) pathway." (PMID 38887915, 2024). "Additionally, a recent report illuminated EGCG blocked NET formation as well as STAT3 and CXCL8 expression in the colon cancer-derived TANs, thereby inhibiting the invasion and migration of colon tumor." (PMID 38348027, 2024). "In addition, the combination of resveratrol and 5-FU also simultaneously inhibited STAT3 and Akt phosphorylation in DLD-1 colon cancer cells." (PMID 39061884, 2024). "Consequently, we observed elevated phosphorylation levels of STAT3 and p65 in LRRK2 G2019S colon tumors, accompanied by upregulation of downstream molecules such as Bcl-xL, cyclin D1 and COX-2." (PMID 38607004, 2024). "It has also been shown that circ-STAT3.46 sponges and suppresses the expression of miR-139-5p, which in turn rescues miR-139-5p-mediated suppression of IGF1R, leading to activation of STAT3 signaling in colon cancer cells in a feedback." (PMID 38185635, 2024). "In colon cancer cells, CXCL8 expression is inhibited by downregulating STAT3." (PMID 39201782, 2024). "Secondly, while we have identified and validated a potential mechanism involving WNT4, STAT3, and IGF2 in colon cancer using sequencing data and immunofluorescence techniques, additional technologies such as WB and PCR are required to verify their regulatory relationships." (PMID 39373342, 2024). "Additionally, multiplex immunofluorescence analyses of pathological sections from 25 patients with colon cancer confirmed co‐expression of WNT4, STAT3, and IGF2." (PMID 39373342, 2024). "Intriguingly, in HCT116 colon cancer cells, although carnosol inhibited STAT3 phosphorylation, it did not affect the level of total cellular STAT3." (PMID 37507889, 2023).
colon carcinoma (continued). "NAP, in addition to inhibiting STAT3, may also inhibit STAT1, thereby inhibiting the expression of CD44, and the stemness of colon cancer." (PMID 36732759, 2023). "Further experimental studies confirmed that intestinal barrier function-related proteins, inflammatory and immune-related signaling pathways (STAT3 and Nod pathways), and free fatty acid receptor 2 (FFAR2) inhibited the “inflammatory transformation” of colon cancer." (PMID 36844438, 2023). "Studies conducted on erlotinib-resistant and non-resistant SW480 colon cancer cells showed that the STAT3 ODN-decoy inhibited the growth of both cell lines." (PMID 38067351, 2023). "In the current study, we set out to establish if LINC00858 affected the progression of colon cancer and revealed that LINC00858 could recruit RAD21 to regulate PCNP-mediated STAT3/5 signaling pathway, thereby promoting the development of colon cancer." (PMID 35468892, 2022). "Furthermore, Jab1/CSN5 knockdown regulates signal transducer and activator of transcription 3 (STAT3) DNA-binding activity and increases STAT3 expression via protein-protein interaction in colon cancer cells." (PMID 35315259, 2022). "Therefore, we found that MTCAF-derived ICAM-1 promotes the progression by activating the STAT3 and AKT signaling in colon cancer cells." (PMID 36016615, 2022). "Multiple experimental, non-marketed inhibitors of STAT3 reduced colon cancer growth in preclinical models." (PMID 35626167, 2022). "In our study, we aimed at evaluating whether pterostilbene, a natural analog of resveratrol, could exert its anticancer activity against human colon cancer cells through the alteration of the AKT and STAT3 signaling pathways." (PMID 35056682, 2022). "By comparison, at 6 h pterostilbene up-regulated transcriptional activity of STAT3 gene in colon cancer cells in relation to control, whereas no marked changes in STAT3 gene activity were demonstrated in cells treated with pterostilbene for 12 h." (PMID 35056682, 2022). "Thus, the results of our studies suggest that pterostilbene suppresses proliferation and induces apoptosis of HT-29 colon cancer cells through down-regulation of both AKT and STAT3 pathways." (PMID 35056682, 2022). "Ab27 suppressed tumor growth in liver and colon cancer xenograft models, including sorafenib-resistant HCC, which occurred concomitantly with a reduction in the phosphorylation levels of FAK, p27Kip1, and STAT3." (PMID 35211652, 2022). "Overall, the results obtained in the current study demonstrated that LINC00858 affects the progression of colon cancer and revealed that LINC00858 is able to recruit RAD21 to upregulate PCNP, which contributes to STAT3/5 signaling activation, thereby promoting the development of colon cancer." (PMID 35468892, 2022). "Taken together, we hypothesized that G-749 effectively reduced phosphorylation of STAT3 and AKT, which are involved in cell proliferation, through the reduction of TYRO3 in colon cancer cells." (PMID 34721022, 2021). "Although the exact mechanism is unknown, studies in colon cancer models have shown that the overexpression of RKIP inhibits IL-6-, Jak-, or Src kinase-mediated phosphorylation of STAT3 known to be necessary for its activation." (PMID 34944867, 2021). "Furthermore, significant positive correlations of CBX4 with STAT1 and IL-6R/STAT3 were observed, and the activation of STAT1 and IL-6/STAT3 signaling has been reported to promote immunosuppression in the TME of colon cancer." (PMID 34222240, 2021). "SJZD can affect NK cell activity and colon cancer proliferation, which may intervene IFN-γ secretion by regulating STAT3 signal and reduce the expression of PD-1/PD-L1, so as to improve NK cells and inhibit the growth of colon cancer cells." (PMID 34868331, 2021). "The high-level p-STAT3 expression is frequently reported in colon cancer, so we suppose that the combination application of AF and ICG-001 may involve in regulation of STAT3-related pathways." (PMID 34900688, 2021).
colon carcinoma (continued). "In addition, G-749 reduced STAT3 and AKT phosphorylation in HCT15 and SW620 colon cancer cells and promoted apoptosis." (PMID 34721022, 2021). "In 2020, Zhang and his team confirmed that P2X7R is involved in the activation of STAT3 signal and the regulation of EMT-related gene expression in colon cancer cells induced by ATP, and the activation of P2X7R can also stimulate STAT3 pathway and regulate the expression of MMP-2 and E-cadherin." (PMID 35002763, 2021). "Immunoprecipitation and western blotting showed that SARI specifically interacts with STAT1, but not STAT3 and NF‐κB in colon cancer cells." (PMID 31578820, 2020). "Moreover, STAT3 and HOTAIR were shown to independently regulate colon cancer cell apoptosis and invasion." (PMID 31953926, 2020). "In the MDA-MB-468 cell line, the decrease in cell viability was dependent on increased phosphorylation of signal transducer and activator of transcription 3 (STAT3), which is not observed in the colon cancer cell lines." (PMID 33291686, 2020). "STAT3 and HOTAIR synergistically regulates the colon cancer cell apoptosis and invasion." (PMID 31953926, 2020). "Furthermore, in colon cancer, the internalized CD44 and acetyltransferase p300 induce STAT3 acetylation at Lysine (Lys) 685, which in turn promotes the expression of cell cycle regulators cyclin D1 70, MYC, and Twist1 in colon cancer cells." (PMID 32754274, 2020). "In an in vitro study, ectopic expression of SARI inhibited p‐STAT1 and STAT1 levels, but had no observed effect on STAT3 and NF‐κB expressions in colon cancer cells." (PMID 31578820, 2020). "This phenomenon was described and explained by Corvinus at al., who showed that some colon cancer derived cell lines (HT-29 was included), contrary to the colon cancer tissues, do not express the active form of STAT3, unless incubated with IL-6." (PMID 32121279, 2020). "However, mRNA level of STAT3 was reported consistent with protein level in gingival epithelial cells and MYC mRNA and protein level was found closely related in colon cancer cells after Fusobacterial infection." (PMID 33391626, 2020). "Infection with P. gingivalis could activate JAK/STAT3 pathway in normal gingival epithelial cells, While F. nucleatum could upregulate MYC in colon cancer cells through E-cadherin pathway." (PMID 33391626, 2020). "Interestingly, when we silenced both HOTAIR and STAT3 in colon cancer cells, the apoptotic rate was higher than knockdown on either HOTAIR or STAT3 alone." (PMID 31953926, 2020). "All three colon cancer cells highly expressed GP130, IL-11, IL-11Rα and p-STAT3." (PMID 30736824, 2019). "Interestingly, we found that many of the DEGs and their regulators were prognostic markers for colon cancer, including CEBPB, PPARGC1, STAT3, MTOR, BCL2, JAK2, and CDK1." (PMID 31186640, 2019). "After we identified the activation of GP130, IL-11, IL-11Rα and STAT3 expression in human colon cancer cells, we confirmed that the neutralized GP130 antibody could reduce the viability of human colon cancer cells." (PMID 30736824, 2019). "Interestingly, AvrA activates the expression of the STAT3 target genes MMP7 (matrix metalloproteinase-7) and SOCS3 (suppressor of cytokine signaling 3) in a colon cancer mouse model." (PMID 31611869, 2019). "CM from tRXRα-transfected but not from RXRα-transfected THP-1 cells enhanced STAT3 activation in human HCT-116 colon cancer cells." (PMID 30931933, 2019). "This study aimed to investigate the relationship between the expression of microRNA (miR)‐181b, protein inhibitor of activated STAT3 (PIAS3) and STAT3, and to examine the function of the miR‐181b/PIAS3/STAT3 axis on the Warburg effect and xenograft tumour growth of colon cancer." (PMID 30054984, 2018). "For example, BCL2 overexpression recruits YP, but not SP, and STAT3 to mitochondria in the human colon cancer cell line HCT116, where it leads to increased O2-production enhancing survival." (PMID 30231582, 2018).